EID1 (EP300 interacting inhibitor of differentiation 1)
Description:
Interacts with RB1 and EP300 and acts as a repressor of MYOD1 transactivation. Inhibits EP300 and CBP histone acetyltransferase activity. May be involved in coupling cell cycle exit to the transcriptional activation of genes required for cellular differentiation. May act as a candidate coinhibitory factor for NR0B2 that can be directly linked to transcription inhibitory mechanisms.
Synonyms: EID-1; C15orf3; CRI1; RBP21; PNAS-22; PTD014; IRO45620
Tractability: PROTAC: UniProt records ubiquitination sites on it; ubiquitination databases record sites on it.
Gene: Protein-coding gene on chromosome 15 (48,878,134 to 48,880,173, forward strand). Ensembl gene ENSG00000255302.
Subcellular location: Nucleus; Cytoplasm
Subcellular location (Human Protein Atlas): Nucleoplasm
Gene Ontology:
Molecular function: histone acetyltransferase binding; protein binding; transcription corepressor activity
Biological process: cell differentiation; negative regulation of DNA-templated transcription; negative regulation of transcription by RNA polymerase II
Cellular component: cytoplasm; nucleoplasm; nucleus
Genetic constraint (gnomAD): Loss-of-function variants: 3 observed, 14.26 expected, observed/expected ratio (o/e) 0.21, 90% interval 0.095 to 0.54. The upper end of that interval is the gene's LOEUF score, 0.54, which puts it in group 2 of 6, group 1 being the genes least tolerant of losing a copy. Missense variants: 261 observed, 263.33 expected, observed/expected ratio (o/e) 0.99, 90% interval 0.89 to 1.1. Synonymous variants: 105 observed, 104.93 expected, observed/expected ratio (o/e) 1, 90% interval 0.85 to 1.18.
Homologues: Orthologues: dog EID1 (89% identical), pig EID1 (89% identical), rabbit EID1 (87% identical), rat Eid1 (63% identical), mouse Eid1 (63% identical), guinea pig EID1 (58% identical). Paralogues in human: EID2 (29% identical), EID2B (21% identical).
Diseases named in the same sentence as EID1 in open-access papers:
EID1 is named in the same sentence as 17 diseases in open-access papers, as found by Europe PMC text mining. Sharing a sentence is not in itself a finding about the gene and the disease. The quoted sentences say what the papers report.
Obesity (2 papers, 2023 to 2024). Accumulation of substantial excess body fat. "EID1, which represses transcription and regulates cell cycle and differentiation, plays a negative regulatory role in obesity and a positive regulatory role in neurodegeneration." (PMID 38094940, 2023).
bipolar disorder (1 paper, 2023). A disorder of the brain that causes unusual shifts in mood, energy, activity levels and the ability to carry out day-to-day tasks. "Finally, regarding the DMR, SNPs within the region comprising the associated genes SHC4 and EID1 have been related with psychiatric disorders such as major depressive disorder, bipolar disorder, mood and psychotic disorders, obsessive compulsive disorder, and schizophrenia." (PMID 36385171, 2023).
gastric cancer (1 paper, 2021). A primary or metastatic malignant neoplasm involving the stomach. "Despite the effect on antivirus immune response and ubiquitination regulation of a few oncoproteins, such as EID1 and P-gp, little is known about the Fbxo21 function in tumors, including gastric cancer." (PMID 33531987, 2021).
Primary microcephaly (1 paper, 2022). Head circumference below 2 standard deviations below the mean for age and gender at birth. "Mutations in CEP152 have been associated with primary microcephaly; SHC4 is mainly expressed in the testes and brain; and EID1 may play a crucial role in lipid accumulation and proliferation of neural stem cells." (PMID 35440892, 2022).
EID1 also shares sentences with these, for which no sentence is quoted: hepatic carcinoma (1 paper); Hypertension (1); liver fibrosis (1); major depressive disorder (1); malignant mesothelioma (1); malignant pleural mesothelioma (1); obsessive-compulsive disorder (1); oculocerebrorenal syndrome of Lowe (1); osteosarcoma (1); pancreatic cancers (1); psychiatric disorder (1); schizophrenia (1); tumor (1).